CD86 (CD86 molecule)
Diseases named in the same sentence as CD86 in open-access papers (continued):
Sharing a sentence is not in itself a finding about the gene and the disease.
infection (continued). "Similar to other DC subsets, these cells were susceptible to infection with hRSV, and while they expressed increased amounts of CD80 and CD86 in response to this virus as compared to non-infected cells, they also expressed the inhibitory costimulatory receptor PD-L1 and secreted IL-10." (PMID 31057543, 2019). "Furthermore, E. coli did not induce CD86, but its expression was decreased after Dex stimuli, even on macrophages without infection." (PMID 29867993, 2018). "In addition, the neonatal mDCs did not upregulate expression of CD86 in response to infection as was observed with the adult mDCs." (PMID 28060871, 2017). "Infection with Y strain did not have a significant effect on the expression of CD80 or CD86." (PMID 26147698, 2015). "Conversely, expression of CD86 was decreased in Mo-DC infected with ncp BVDV1b TGAN, ncp BVDV2a 28508-5 or ncp BVDV2a 1373 from 100% at 0 hour to 72.64 ± 1.38% (i.e. 28%), 76.31 ± 11.03% (i.e., about 24%) or 71.36 ± 4.08% (i.e., roughly 29%) at 72 hours post-infection, respectively." (PMID 24607146, 2014). "Alternatively, Tregs may require CD86 in the context of a classic APC, and we have observed that MHC II+ mononuclear cells in the respiratory tract late after infection may express either CD80 or CD86 or both (data not shown)." (PMID 25144228, 2014). "This hypothesis was tested in this study and found that always females have higher expression of MHC-II, CD80, CD86, PD-L1, and PD-L2 during infection, but not in response to saline or TcEx." (PMID 23533995, 2013). "However, our data did not provide any evidence that pre-patent infection impaired the expression of MHC class II or CD86 by either APC population, or diminished their numbers in either liver or spleen." (PMID 23556020, 2013). "mRNA expression measured at various time points (1, 3, 12, 24, 36 and 48 hpi) by real-time RT-PCR showed that infection of PK-15 cells with CSFV at either a MOI of 0.1 or 1.0, resulted in down-regulation of seven immune response genes, namely SLA-2, TAP1, SLA-DR, Ii, CD40, CD80, CD86." (PMID 22925563, 2012). "Neither infection status nor the interaction between infection status and age group influenced expression of CD86 on mDC as determined by ANOVA, which was confirmed by post hoc tests comparing CD86 expression between un-infected and infected people after partitioning into age group." (PMID 23029585, 2012). "Costimulatory molecules (CD80, CD86, CD40, GITR, and ICOS), adhesion molecules (VCAM-1 and P-selectin), and signaling molecules involved in cytokine regulation (Tbx21 and Socs1) were also increased with Hb infection and decreased with anti-IL-7Rα M595 treatment in a dose-dependent manner." (PMID 23057802, 2012). "However, on day 4 post infection, the frequencies ofthe activation markers CD40+ and CD86+ on mDCwere significantly higher in the TLR group (4.418% ±0.231%SEM) compared to all other groups (DENV/TLR: 3.66% ±0.080%SEM, p<0.021; DENV: 0.950%±0.320% SEM, p<0.001;Control: 1.233% ±0.190% SEM,p<0.001)." (PMID 21559444, 2011). "Indeed, we were not able to detect IFN-α production by ELISA, which correlates with the absence of CD86 expression on cDCs after infection with NYVAC-C-KC-ΔB19R." (PMID 21347234, 2011). "Despite that M1 macrophages typically upregulate MHC-II and costimulatory molecules, we could not detect an increased expression of MHC-II or CD86 on gastric macrophages or CD103+ DCs from either unimmunized or immunized mice after infection." (PMID 21124899, 2010). "In this study, CD86 expression on B cell was not significantly different between these two models early in infection, but diverged later with increased levels of Balb/c B cells at day 28 post-infection concomitant with peak hypergammaglobulinemia in these mice." (PMID 20625554, 2010). "In addition, in the absence of CD40, CD40L or CD80/CD86, viral reactivation in the lungs was observed at later time points after infection." (PMID 19621080, 2009).
infection (continued). "Interestingly, the PD-L1 was mostly expressed on the surface of the M1 macrophages (CD86+) during the early infection (1–3 weeks), but not on the CD206+ M2 macrophages, while the PD-L2 was mostly expressed on the CD206+ M2 macrophages during the late stage of infection." (PMID 36668953, 2023). "Furthermore, macrophages increased the expression of activation markers (CD80, CD86 and CD40) that was more evident at week 10 after infection while DCs of Treg depleted mice increased the expression of CD86 and CD40 at week 6 and CD80 and CD40 at week 10 after infection." (PMID 30410119, 2018). "CD86 blockade on the tempo of virus clearance as determined either by infectious virus titer or viral genome copy number, consistent with an earlier report from our lab showing that CD86 blockade early during infection (i.e. day 5 p.i.)did not affect virus clearance." (PMID 25144228, 2014). "In summary, infection of microglia with MP-12 and ZH501 yielded different outcomes, with downregulation of CD45 and CD1b and no induction of CD86 and CD80 expression in response to ZH501 infection." (PMID 38392897, 2024). "Znfx1–/– BMDMs expressed significantly reduced levels of CD80, CD86, and MHC-II in response to H37Rv infection, without influencing the expression of CD206, a marker of type II macrophages." (PMID 38016036, 2024). "When quantifying the cell membrane markers, we found that after 1.5 h of infection, macrophages infected with vegetative P. aeruginosa cells expressed high levels of CD80/CD86, but not CD206." (PMID 36920189, 2023). "Intriguingly, the effect of itaconic acid pre-stimulus on macrophages, in the absence of infection or IFNG activation, was upregulation of Icosl and downregulation of Cd86, with statistically significant differences compared to the control." (PMID 37235312, 2023). "DN2 cells from severely infected SARS-CoV-2 subjects had significantly higher levels of CD69 expression, but not CD86, when compared to individuals immunized against SARS-CoV-2 or those with mild infection." (PMID 36131937, 2022). "The expression of MHC II, CD86, and CD80 was not differentiable between infection routes for mDCs and CD8+ DCs, whereas there was a higher expression on pDCs in i.p. infected mice." (PMID 35898505, 2022). "In contrast, U266-84 cells did not express CD86 and displayed the greatest reductions in CD70 and ICAM-1 upon LOAd infection." (PMID 32355275, 2020). "In stark contrast to normal iDCs, however, LADIII iDCs did not upregulate the CD86 molecules in response to HTNV and TULV, respectively, at 12 h after infection." (PMID 32596167, 2020). "In contrast, infection with Ad5[P] or Ad5[PVP2]OP at MOI 250 led to a twofold increase of the MHC-II, CD80, and CD86 expression levels as compared to non-infected BMDCs." (PMID 33250878, 2020). "Whereas previous reports, analyzing late points after infection, were not able to show activation by DCs upon CVB3, our findings show that WT DCs up-regulate CD80 and CD86 as early as 6 hours after CVB3 infection." (PMID 28973047, 2017). "There was no significant change in pDC HLA-DR, CD86 or CD123 expression, either without stimulation (NIL) or following TLR7 or TLR9 stimulation, when baseline was compared to peak-infection in eight individuals." (PMID 28572564, 2017). "Like LASV, MOPV infection also fails to activate DCs in culture as evidenced by the failure to upregulate CD80, CD86, CD54, CD40, and HLA-abc." (PMID 28498311, 2017). "CD86 was restored to normal levels with both ALE (18.7%) and ASE (18.5%) at 100 mg/kg bw and the changes were not significant in relation to infection control (P > 0.05)." (PMID 25884649, 2015). "Infection with Col cl1.7, but not with Y strain, led to an increase in the expression of CD80 and CD86." (PMID 26147698, 2015). "With increased time of infection, the expression of M1-type molecular markers such as CXCL11 and TNF-α significantly decreased, with the exception of CD86, which showed no significant change." (PMID 26091535, 2015).
infection (continued). "Administered before infection, neither anti-CR1 (CD35) nor anti-CR3 (CD11b) affected the stimulatory capacity of monocytes, as evaluated by expression of CD86, CD40 and HLA-DR (data not shown)." (PMID 25061945, 2014). "Here, the expression of CD68, CD80, CD86, HLA-DR, MMR, TLR2 and TLR4 was analyzed under different experimental conditions (plus or minus exposure to CS, and with or without Mtb-infection)." (PMID 24278357, 2013). "Here, we show that a non-productive infection of HHV-6A in DC leads to the up-regulation of HLA-ABC, via autocrine IFN-α signaling, as well as the up-regulation of HLA-DR and CD86." (PMID 23526966, 2013). "In contrast, upon EV1 infection there was no further increase of CD80, CD86 or PDL1 expression compared to non poly I:C-stimulated, EV1-infected cells." (PMID 23638101, 2013). "cLN analyzed at 12 hours post-infection demonstrated no increase in CD69, CD80, or CD86 under any conditions (data not shown)." (PMID 22393351, 2012). "Surprisingly, the expression of CD86 and MHC-II by either gastric macrophages or CD103+ DCs was not increased after infection with H. pylori relative to age-matched naïve mice analyzed in parallel." (PMID 21124899, 2010). "While CD68 expression did not change with infection or treatment, Mtb infection resulted in the elevated expression of HLA-DR and CD200R, while activation markers such as CCR7, CD80/CD86, and CD64 as well as scavenger receptors CD163 and CD206 were reduced on Mtb-infected cells." (PMID 40305296, 2025). "Moreover, the infection of moDC downregulates CD86 expression but not MHCII, and the Akt inhibitor reestablishes CD86 expression and 12p40 production." (PMID 38787051, 2024). "Interestingly, MP-12 infection elicited robust expression of both CD86 and CD80, whereas ZH501 infection did not lead to significant upregulation of either protein." (PMID 38392897, 2024). "During infection, no obvious modulation of CD40 and CD86 on LN MΦs was observed." (PMID 38012553, 2023). "While the amounts of macrophages and dendritic cells in the spleen and bone marrow display no collective trend during infection, the presence of mature populations expressing MHCII and CD86 are significantly increased during the early phase of infection (day 1.5 and d 3) p.i. in both organs." (PMID 34202636, 2021). "Interestingly, P.gingivalis significantly reduced constitutive CD86, and CD80 levels in oDCs (51.06%, 47.8%) compared to control oDCs with no infection (27.6% and 33.9%) respectively." (PMID 34141629, 2021). "In the spleen, P. berghei K173 infection induced a global activation of lymphocytes and DC, as exemplified by the upregulation of CD69 on T cells, B cells, and NK cells (not shown), and of CD86 on DC." (PMID 32265335, 2020). "It should be noted that during the course of the respective antigen presentation experiments (48 hpi), siRNA-mediated silencing of Beclin-1 and Atg7 did not affect expression and/or infection-dependent induction of surface MHC I (H-2Kb and H-2Db), CD80, CD86, PD-L1 or PD-L2." (PMID 28634388, 2017). "However, during the course of infection, the number of CD11c+MHCII+CD86+ cells did not change in either infection." (PMID 27073297, 2016). "Finally, we were able to reduce immunodominance after i.d., but not i.p. infection, using a VACV expressing the costimulators CD80 (B7-1) and CD86 (B7-2), which is notable because VACV-based vaccines incorporating these molecules are in clinical trials." (PMID 23633956, 2013). "Moreover, while the primary T-cell response to infection is CD80/CD86-dependent on secondary infection, memory helper T cells do not require CD80 or CD86 costimulation for their activation to protect against challenge." (PMID 23053394, 2012). "We have shown previously in mice, that infection with live viruses, including influenza/A and Semliki Forest virus (SFV), induces systemic partial activation of lymphocytes, characterized by cell surface expression of CD69 and CD86, but not CD25." (PMID 21998693, 2011).
infection (continued). "At 5 weeks post-infection, when the duodenum is chronically infected with this parasite, the MLN show an almost complete absence of CD8αint, effectively removing the highest CD86-expressing cells from the MLN (data not shown)." (PMID 19766674, 2009). "In fact, although we observed significantly lower baseline levels of the MHC II and costimulatory molecules, CD86 and CD40 on DCs in the absence of TLR4, the maturation and induction of these molecules was comparable to that of cells expressing TLR4 in response to hMPV infection." (PMID 24205331, 2013). "Significant (p < 0.05) up regulation in cell surface expression of CD40, CD80, CD54 and MHC class II and CD86 and CD83 were observed both in LPS stimulated and H37Rv infected in comparison to negative control DC with media alone without any stimulation/infection." (PMID 21777464, 2011).
cancer (311 papers, 2003 to 2026). A tumor composed of atypical neoplastic, often pleomorphic cells that invade other tissues. "The increased association between dendritic cells and T cells via CD86 signaling prompted us to explore immune activation in cancer." (PMID 37700026, 2023). "CD86 was overexpressed in many cancers, and its overexpression was associated with a poor prognosis." (PMID 37064861, 2023). "Spearman correlation coefficients were used to analyze the association between CD86 and these four gene sets in different cancer types." (PMID 37064861, 2023). "Co-incubation of bone marrow-derived dendritic cells (BMDC) with ML162, RSL-3 and Erastin-induced ferroptotic cancer cells cause increased exposure of CD86, CD40, and MHCIIhigh indicative for strong DC maturation." (PMID 35760796, 2022). "In the present study, we targeted rs1129055 and rs17281995 of the CD86 gene and performed a meta-analysis with an aim to present compelling statistical evidence for their genetic predisposition to cancer." (PMID 25369324, 2014). "The first strong point is that this is the first study examining the associations between CD86 polymorphisms and cancer risk to date, and the associations were assessed using a rigorous method." (PMID 25369324, 2014). "By using the search terms Cluster of Differentiation 86/CD86/B7-2/polymorphism/polymorphisms/cancer, we searched PubMed, Embase, CNKI, and Wanfang and identified four studies for rs1129055 (2137 subjects) and rs17281995 (2856 subjects) respectively." (PMID 25369324, 2014). "Firstly, even though we have summarized all data on CD86 polymorphisms and cancer risk, the total sample still needs further expansion." (PMID 25369324, 2014). "Previous studies concerning the role of CD86 polymorphisms (rs1129055 and rs17281995) in cancer fail to provide compelling evidence." (PMID 25369324, 2014). "We finally identified six publications of CD86 polymorphisms and cancer risk." (PMID 25369324, 2014). "Whether CD86 polymorphisms could serve as a biomarker for genetic susceptibility to cancer requires to be further validated in future." (PMID 25369324, 2014). "qRT-PCR analysis revealed that TAMs cocultured with MMP28-knockdown cancer cells presented upregulated CD86 expression and downregulated CD163 expression." (PMID 39972459, 2025). "CTLA-4, a transmembrane protein expressed on T lymphocytes, competitively binds to ligands CD80 (B7.1) and CD86 (B7.2) on antigen-presenting cells (APCs), and prevents T-cells from killing other cells, including cancer cells." (PMID 40563393, 2025). "Antigen-presenting molecules like MHC-I, MHC-II, co-inhibitory molecules (CTLA4), or co-stimulatory molecules (CD80, CD86) are crucial for presenting cancer antigens to T cells and triggering an immune reaction." (PMID 39980072, 2025). "This is supported by recent studies, which have shown that blockade of CD80 and CD86 following immunotherapy can improve outcomes in preclinical cancer models." (PMID 41417245, 2025). "TAM Macro‐2 loses the expression of CD86, a potent co‐stimulatory signal necessary for T cell activation and survival, and is almost exclusively found in patients with cancer; therefore, we termed this subset TAM Macro‐2." (PMID 38483933, 2024). "Instead, Akt inhibition led to a significant increase in CD11c+/CD86+ populations across all stiffnesses and cancer types." (PMID 39211033, 2024). "In cancer co–cultures, CD86+ populations decreased on higher stiffnesses across four different cancer types." (PMID 39211033, 2024). "Cancer cells can evade the host’s immune system by overexpressing B7 family molecules (such as CD86 or PD-L1), which repress T-cell antitumor responses by binding to the PD-1 receptor." (PMID 39599846, 2024). "Compared to Mo‐DC from cancer patients, healthy Mo‐DC expressed higher levels of HLA‐DR, CD86, CD83, and CCR7." (PMID 38351552, 2024).